DDIT4 (DNA damage inducible transcript 4)
Diseases named in the same sentence as DDIT4 in open-access papers (continued):
Sharing a sentence is not in itself a finding about the gene and the disease.
tumor (continued). "First, the heterogeneity in TIME functional changes induced by DDIT4 overexpression across different tumor types remains inadequately explained, necessitating further analysis based on the biochemical or pathological characteristics of specific tumors." (PMID 40900790, 2025). "This review highlights the impact of these effects on TIME, aiming to provide evidence supporting DDIT4 as a novel target for tumor immunotherapy." (PMID 40900790, 2025). "We analyzed DDIT4 expression in 33 tumor tissues and corresponding normal tissues in the TCGA and GTEx databases." (PMID 38507057, 2024). "At the same time, we used GEPIA2.0 website to investigate DDIT4 expression in different tumor stages." (PMID 38507057, 2024). "DDIT4 was highly expressed in MM, and after knockdown prompted apoptosis of MM cells, impairing tumor migration and invasion ability." (PMID 38079253, 2024). "Clinicopathological factor and survival analyses based on TCGA data revealed that the larger the tumor size, the higher is the Gleason score, and that patients with metastasis exhibited high DDIT4 expression." (PMID 38384328, 2024). "Based on these findings, we can conclude that the anti-tumor effect of TGR5 activation in the CC xenograft was partially achieved via modulating the HCP5/miR-139-5p/DDIT4 axis in vivo." (PMID 39201624, 2024). "The findings of our study indicated a statistically significant increase in the median expression levels of DDIT4 in patients with moderate/poor tumor differentiation in comparison to those with well-differentiated tumors (P = 0.015)." (PMID 37938616, 2023). "KDM4A promotes HIF1α expression by inhibiting histone methylation in the HIF1α promoter region, thereby upregulating DDIT4 expression and activating the mTOR signaling pathway to promote tumor proliferation, migration, and invasion." (PMID 36611207, 2023). "Enhancing DDIT4 expression has been shown to be an effective strategy for inhibiting the growth of a variety of tumours by repressing mTOR activity and the phosphorylation of the downstream protein S6." (PMID 36681687, 2023). "A previous in vivo report revealed that miR-221 overexpression promoted tumor growth and invasion through the modulation of the mTOR pathway via DNA damage-inducible transcript 4 (DDIT4)." (PMID 37685331, 2023). "The results of RT-qPCR showed that the expression of DDIT4 in tumor samples was higher than in normal samples which was associated with high tumor grade (P = 0.015) and lymphovascular invasion (P = 0.048)." (PMID 37938616, 2023). "DDIT4, located in the cytosol, is related to the response to hypoxia, which plays a vital role in aerobic glycolysis in the tumor microenvironment." (PMID 36768316, 2023). "Previous studies have shown that conditions such as hypoxia and stress can up-regulate DDIT4 expression, but notably, the role of DDIT4 in tumors appears to be paradoxical and tumor environment-dependent." (PMID 36601406, 2022). "We also demonstrated that DDIT4 inhibited tumor formation in a xenograft tumor mouse model under hypoxia." (PMID 36110952, 2022). "High expression of DDIT4 is associated with overall survival (OS) and relapse-free survival (RFS) shortening in most tumor types." (PMID 36601406, 2022). "Correspondingly, we discovered that DDIT4 knockdown promoted cell apoptosis and impaired tumor migratory and invasive potential." (PMID 36110952, 2022). "Our analysis further suggested that DDIT4 is a potential target to mediate the autophagy induction to sensitize tumor cells to etoposide." (PMID 36289218, 2022). "For estimating expression levels of DDIT4, three scoring systems were employed incorporating intensity of staining, percentage of positive tumor cells, and the H-score." (PMID 34211002, 2021). "The results showed that DDIT4 expression was significantly higher in tumor cell lines than in HBE cell lines." (PMID 34659532, 2021).
tumor (continued). "The data of the Kruskal–Wallis test exhibited statistically significant differences between the median nuclear expression level of DDIT4 and tumor differentiation groups as well as various TNM stages (I–IV) (P < 0.05)." (PMID 34211002, 2021). "The results showed that the mRNA levels of DDIT4 were significantly increased in tumor tissues compared to normal tissues." (PMID 34659532, 2021). "Mann–Whitney U test also showed a significant difference in median nuclear expression level of DDIT4 between well and moderately differentiated groups of tumor differentiation (P = 0.037)." (PMID 34211002, 2021). "High tumor expression of DDIT4 was significantly correlated with poorer overall survival in patients with LUAD (P < 0.05)." (PMID 34659532, 2021). "Our findings demonstrated increased expression levels of DDIT4 and TPTEP1 in CRC were associated with more aggressive tumor behavior and more advanced stages of the disease." (PMID 34107956, 2021). "In conclusion, findings of this study highlighted overexpression of DDIT4 as a biomarker in CRC tissues especially in nucleus of tumor cells." (PMID 34211002, 2021). "The Spearman’s correlation test indicated a significant direct correlation between nuclear expression of DDIT4 with tumor differentiation and TNM stages (P < 0.05)." (PMID 34211002, 2021). "The authors showed that miR-221 is overexpressed in both HCC and cirrhotic human livers, and enhances tumor growth through DDIT4 targeting and deregulation of the PI3K-PTEN-AKT-mTOR pathway." (PMID 32717951, 2020). "DDIT4, a regulator of the mammalian target of rapamycin (mTOR) kinase, has been shown as an important protein in tumor development due to its tumor suppressing properties." (PMID 32717951, 2020). "Above data manifested that DDIT4 is the factor directly downstream of miR-496 and exerts a tumor-inhibitory function in PCa." (PMID 32982585, 2020). "In conjunction with the temozolomide-mediated DDIT4 induction, these results suggest DDIT4 as a physiological resistance mechanism of tumour cells to temozolomide." (PMID 30745581, 2019). "The mouse model experiment further demonstrated that DDIT4 downregulation significantly inhibited tumor growth in vivo." (PMID 29976242, 2018). "In this work we analyzed publicly available online datasets with the purpose of evaluate DDIT4 expression as possible biomarker in the outcome of several tumor types." (PMID 28484222, 2017). "Studies have shown that 1,25D3 or its analogues can suppress tumor cell growth by upregulation of Ddit4 in various cancer cell model systems." (PMID 27898044, 2016). "miR-221 is capable of stimulating tumor growth in vivo, possibly through down-regulation of p27 and/or DDIT4 expression." (PMID 25337143, 2014). "Ddit4 is a known tumor suppressor whose expression has shown to be down regulated in a subset of human cancers." (PMID 22934068, 2012). "Within the top 20 genes ranked by Notch pathway-guided COCA, there are several genes related to differentiation (Tdgf1, Egr1 and Lefty1), cell growth (Ddit4, Hk2, Phlda2, Egln3 and Igfbp1) and tumor/cancer development (Afp, Sfrp2, Egr1, Hk2 and Phlda2)." (PMID 20353603, 2010). "DDIT4 is a regulatory factor that is commonly overexpressed in tumor tissues." (PMID 40900790, 2025). "DDIT4-mediated autophagy activation through PI3K-Akt/mTOR pathway inhibition in tumor cells potentially regulates the expression of MHC-I molecules and immune checkpoint proteins, suggesting a critical link between cellular stress responses and tumor immunogenicity." (PMID 40900790, 2025). "Finally, the radiation-induced upregulation of DDIT4, by acting as a negative regulator of mTOR, induces anti-tumor therapy resistance." (PMID 38339228, 2024). "For example, DDIT4, a factor involved in regulating cell survival and proliferation, is essential for the survival of some cancer cell lines but may be tumor suppressive in others." (PMID 36681780, 2023).
tumor (continued). "Notably, immune infiltration analysis showed that the levels of DDIT4 expression correlated negatively with the abundance of tumor-infiltrating immune cells and immune biomarker expression, but correlated positively with immune checkpoint molecules." (PMID 37391802, 2023). "According to the analysis of data from TIMER, the abnormal expression of DDIT4 may alter the tumor microenvironment and immune response, which can significantly affect clinical outcomes." (PMID 37391802, 2023). "It has been reported that DDIT4 plays an essential role in tumor progression." (PMID 37715019, 2023). "We further examined these function-related genes by RT-PCR, and we found that the relative expression of the DDIT4 was the lowest in the rapamycin + etoposide group compared to rapamycin or etoposide alone, which was consistent with tumor volumes of four groups in a xenograft model." (PMID 36289218, 2022). "Some studies have found that RIMKLB can affect reproductive function of mammals, and in tumor research, RIMKLB may coordinate with DDIT4 function to mediate mTOR inhibition and growth inhibition of tumor cells." (PMID 35444692, 2022). "Clustering analysis of BMDCs and MDSC-DCs in the genes of mTOR signaling pathway found that tumor suppressor factors such as Pten, Tsc1, Ddit4, mtor, Rptor, and other genes involved in controlling the activity of rapamycin complex 1 (mTORC1) were found in MDSCs-DCs and are all down-regulated." (PMID 36567953, 2022). "In vitro studies have suggested that DNA damage-inducible transcript 4 (DDIT4) could be a tumor suppressor or an oncogene in cancer, depending on the context." (PMID 36400857, 2022). "On the other hand, high expression of DDIT4 can protect human cancer cells from hypoxia-induced cell death through stabilizing HIF1α in downstream of the suppressed mTOR pathway which followed by occurs increased cell survival and tumor growth." (PMID 34211002, 2021). "However, a significant overexpression of DDIT4 at nucleus was observed in tumor cells compared to adjacent normal tissue samples (P = 0.003)." (PMID 34211002, 2021). "Overexpression of DDIT4 protein may indicate more aggressive tumor behavior and more advanced disease in the patients with CRC." (PMID 34211002, 2021). "Previous literatures suggested that DDIT4 was closely related to autophagy in tumor cells." (PMID 34007269, 2021). "In CRC samples, more strong intensity and higher median expression of DDIT4 in nuclear staining for tumor tissues might be due to the role of DDIT4 in the cancer cells҆ nucleus." (PMID 34211002, 2021). "Notably, DDIT4 induction conferred GB cell resistance to external stimuli such as temozolomide and radiotherapy as well as tumour-intrinsic stimuli such as nutrient and oxygen deprivation." (PMID 30745581, 2019). "Furthermore, DDIT4 also protected cells under conditions of tumour microenvironment with glucose and oxygen deprivation." (PMID 30745581, 2019). "Therefore, DDIT4 is a potential target for therapeutic inhibition to disrupt tumour cell adaptation and sensitise GBs to the effects of the established treatment regimens." (PMID 30745581, 2019). "Finally, we observed a reduced Ki67 (proliferation marker)-positivity rate in tumor tissues in the DDIT4-knockdown group compared with the control group." (PMID 29976242, 2018). "These processes sustain that the dysregulation of DDIT4 degradation could be a common event that elevates mTOR signaling during tumor development." (PMID 29707520, 2018). "Results of in vitro studies suggest that DDIT4 could have a context-dependent contrasting role in cancer as oncogene or tumor suppressor." (PMID 29707520, 2018). "Moreover, several lines of evidence demonstrate that DDIT4 is involved in anti-tumor chemotherapeutic treatment." (PMID 29976242, 2018).
tumor (continued). "DDIT4 depletion resulted in a significant reduction in tumor growth." (PMID 29976242, 2018). "However, under cellular stress conditions (such as hypoxia or cytotoxic chemotherapy), mTOR activity is disadvantageous for cancer cells and the suppression of mTOR activity by DDIT4 is important for tumor survival." (PMID 28484222, 2017). "In addition, ectopic DDIT4 expression in Müller cells was sufficient to VEGF expression in the murine model suggesting a potential role in tumor angiogenesis." (PMID 28484222, 2017). "CR mediated up-regulation of the Ddit4 transcript could be one of many ways by which CR exerts its anti-tumor effect." (PMID 22934068, 2012). "Finally, given that the TME is a complex ecosystem composed of various cellular and non-cellular components, the expression and functional levels of DDIT4 in different cell types, as well as its overall contribution to tumor immunity, require further clarification." (PMID 40900790, 2025). "Among these upregulated genes, Dennd4a, Nfil3, Hspa1b, Chac1, Ddit4, Mex3b, Lysmd3, and Zbtb10 are mainly involved in oxidative stress and inflammation response, whereas Plcxd2, Dusp1, Cep85l, and Dusp8 are generally considered as tumor‐suppressor genes by inhibiting proliferation of cancer cells." (PMID 40231790, 2025). "Consequently, it appears that DDIT4 may act as a tumor-suppressing role in the progression of cancer." (PMID 37938616, 2023). "Moreover, upregulation of DDIT4 expression contributes to the reduction of apoptotic processes and promotes proliferation, migration, and invasion of tumor cells in in vitro and in vivo tumor studies." (PMID 37715019, 2023). "Additionally, DDIT4 gene is introduced as a cell intrinsic regulator for cancer therapy resistance in some cancers like brain, lung and gastric because it confers protection of tumor cells from therapy." (PMID 34211002, 2021). "The high expression of DDIT4 not only promotes the increase of autophagy in pancreatic cancer tumor cells but also may be involved in tumor resistance by inhibiting the function of immune cells around the tumor." (PMID 34007269, 2021). "However, it is still controversial to deem DDIT4 as a tumor suppressor." (PMID 34565301, 2021). "CST significantly suppressed CCN2, LOXL2, DDIT4, and FN1, key drivers of ECM remodeling and angiogenesis, indicating that CST disrupts the structural and metabolic axes sustaining tumor progression." (PMID 41279995, 2025). "Regarding the regulation of DDIT4 on TANs, in NSCLC cell lines H-1299 and A549, DDIT4 facilitates the recruitment of TANs under hypoxic; these TANs, typically exhibit immunosuppressive properties in TME and can promote tumor growth, migration, and invasion." (PMID 40900790, 2025). "As we expected, RRM2, SLC2A1, DDIT4, and VDAC2 were significantly upregulated transcriptionally and translationally in tumor samples, whereas PEBP1 and IL33 are significantly reduced in tumorous tissues." (PMID 39311766, 2024). "Upon analyzing the expression of 11 model genes in prostate PRAD, we observed significant differential expression of eight genes (MYADM, MPDZ, LTBP2, DENND4C, PROK1, DDIT4, IGFBP3, and CFD) between normal and tumor tissues." (PMID 38898043, 2024). "Murine xenograft studies demonstrated that TGR5 suppressed the tumor formation of CC cells and downregulated HCP5 and DDIT4 while increasing miR-139-5p in the xenografts." (PMID 39201624, 2024). "Overall, these findings suggested that RRM2, SLC2A1, DDIT4, and VDAC2 were potential oncogene, whereas PEBP1 and IL33 were candidate tumor suppressor genes." (PMID 39311766, 2024).
tumor (continued). "Immunohistochemical staining results of HPA database showed that DDIT4 expression decreased in KICH and PARD tumor tissues and increased in LUAD tumor tissues, this is consistent with the results of pan-cancer analysis." (PMID 38507057, 2024). "The protein levels of DDIT4, TUBA4A, and PTTG1 were markedly elevated in tumor tissues, whereas SLA and BTG2 were notably diminished compared to normal tissues." (PMID 38200058, 2024). "miR-221 targets key tumor suppressors, including CDKN1B/p27, CDKN1C/p57, PTEN, TIMP3, and DNA damage-inducible transcript 4 (DDIT4)." (PMID 33572780, 2021). "The expression levels of ALOX12B, GPX2, DDIT4, GDF15, and RRM2 in tumor tissues were significantly higher than those in the normal lung tissues." (PMID 34307361, 2021). "Among them, DDIT4 and HNF4A were highly expressed in tumor tissues, whereas ALOX15, IL33, and GDF15 were lowly expressed." (PMID 34434660, 2021). "The upregulated ACSL3, DDIT4, RRM2, and SLC2A1 with HR > 1 were considered as oncogenes, whereas the downregulated HERPUD1 and PEBP1 with HR < 1 were regarded as tumor suppressors." (PMID 34499810, 2021). "We observed positive correlates of nuclear DDIT4 expression with the TNM stages and tumor differentiation." (PMID 34211002, 2021). "Finally, we found that DDIT4 gene expression was significantly increased in the hypoxic environment compared to the normal oxygen environment, indicating that the DDIT4 gene may play an important role in the hypoxic microenvironment of tumor tissue." (PMID 34659532, 2021). "Incubation under hypoxic conditions (0.1% oxygen), as can be found in the tumour microenvironment, triggered HIF-1α stabilisation and induced DDIT4 gene expression and protein with decreased phosphorylation of RPS6 as evidence for mTORC1 inhibition." (PMID 30745581, 2019). "REDD1/DDIT4 is known to be inhibitor of mTOR signaling and thereby possess tumor suppressive properties by inhibition of protein synthesis and cell survival." (PMID 31835318, 2019). "Concluding that TNBC and HER2 overexpression showed the highest cell proliferation and survival in a hypoxic tumor environment by activation of the mTOR pathway and HIF-1α stabilization via DDIT4 downregulation." (PMID 29707520, 2018). "The key miR-221-targeted tumor suppressors include p27, p57, phosphatase and tensin homolog (PTEN), a tissue inhibitor of metalloproteinase-3 and the DNA damage-inducible transcript 4 (DDIT4 )." (PMID 25337143, 2014). "Similarly, DHCR7 (cholesterol biosynthesis), DDIT4 (mTOR regulation under stress), HNRNPAB (RNA splicing), and SLC39A8 (zinc signaling) all reflect well-documented mechanisms of tumor growth or adaptation." (PMID 40941703, 2025). "Inhibition of DDIT4-mediated mTORC1-dependent autophagy may enhance tumor antigen presentation via MHC-I, potentially promoting anti-tumor immune surveillance." (PMID 40900790, 2025). "Additionally, the protein expression levels of SLA, BTG2, DDIT4, TUBA4A, and PTTG1 in LUAD tumor tissues and normal tissues were investigated using the Human Protein Atlas (HPA) database." (PMID 38200058, 2024). "The level of DDIT4 expression correlated positively with the infiltration of CD4+ T cells (Cor = 0.081, p < 0.05), neutrophils (Cor = 0.097, p < 0.01), and dendritic cells (Cor = 0.102, p < 0.01) and negatively with tumor purity (Cor = − 0.179, p < 0.001)." (PMID 37391802, 2023). "The protein expression levels of DDIT4 were evaluated using the IHC technique on TMA sections by three distinct scoring methods that comprise the intensity of staining, percentage of positive tumor cells, and H-score." (PMID 37938616, 2023). "In the present study, the overexpression of DDIT4 was detected in approximately half of the pan-cancer datasets in the TIMER database, and the expression of this gene showed the greatest difference between normal breast and tumor tissues." (PMID 37391802, 2023).